CXCL13 (C-X-C motif chemokine ligand 13)
Diseases named in the same sentence as CXCL13 in open-access papers (continued):
Sharing a sentence is not in itself a finding about the gene and the disease.
lymphoma (continued). "Although the size of study cohort is rather small, not permitting elaborated analyses, we found that CXCL13 serum, but not saliva, levels are associated with disease characteristics indicative of systemic active disease and lymphoma, supporting its role in disease pathogenesis." (PMID 34484201, 2021). "However CXCL13 is also expressed in other inflammatory diseases driven by lymphoid organization, for example Sjogren’s syndrome, where levels correlate with the extent of salivary gland inflammation and subsequent lymphoma development." (PMID 33292827, 2020). "Elevated CXCL13 levels in the CSF have been demonstrated for CNS lymphomas, and when elevated together with IL-10 in the CSF, CXCL13 has a >99% specificity for primary and secondary lymphomas, leading to similar proposals that it serves as a biomarker for non-Hodgkin lymphoma involving the CNS." (PMID 31354634, 2019). "Thus, considering its association with lymphoma and the activation of PI3K/AKT pathway, CXCL13 might have a positive correlation with the aggressiveness of ENKTL because latent membrane protein 1, an EBV oncoprotein could activate the PI3K/AKT pathway in ENKTL." (PMID 25966773, 2015). "Our results identify CXCL13 as potentially being an important molecule linking the innate immune system and tumor cells in the pathogenesis of AIDS-lymphoma." (PMID 23936541, 2013). "As few mouse models of AIDS-lymphoma currently exist, our aim in these studies was to create a mouse/human xenograft model of AIDS-BL and to evaluate CXCR5 and CXCL13 expression in this model." (PMID 23936541, 2013). "Further studies are needed to more definitively define the role of the CXCR5/CXCL13 axis, both in murine models, and in human AIDS-lymphoma." (PMID 23936541, 2013). "However, it also seems possible that some of these mechanisms could prove to be unique to AIDS-NHL, given our previous finding that HIV infection is associated with an overproduction of CXCL13, even in subjects who do not develop lymphoma." (PMID 21490903, 2010). "There were no statistical differences between the expressions of CXCL13 in lymphomas of the TFH spectrum (SMLPD: 20%, PCTFHL: 30%, cAITL: 16.5%, p = 0.79)." (PMID 37081015, 2023). "CD47 promotes chemokine-mediated migration of lymphoma cells and by its blockade, it has been demonstrated that this molecule possesses a notable role in the migration of these cells toward known lymphoma chemo attractants SDF-1α and CXCL13." (PMID 32902664, 2021). "In previous studies, the lymphoma cells from all the lymph node with AITL were positive for both PD-1 and CXCL1322, but PD-1 was expressed more prominently (in terms of percentage and intensity) than CXCL13." (PMID 31101882, 2019). "The immunohistochemistry with tumor tissue showed the positive staining for CXCR5 and negative for CXCL13 on lymphoma cells." (PMID 25966773, 2015). "Further, we did not identify any competing diagnosis (for example, lymphoma or cryoglobulinemia) or therapy to account for the very high levels of CXCL13." (PMID 24766912, 2014). "CXCL13 has been more directly implicated in the biology of some B cell tumors, including several non-HIV-associated lymphomas, such as follicular lymphoma and primary intraocular lymphoma." (PMID 23936541, 2013). "Second, these results are consistent with our previously published results that most primary human AIDS-lymphomas, including tumors of the Burkitt subtype, were positive for both CXCR5 and CXCL13 expression, and that serum levels of CXCL13 were elevated in subjects who developed AIDS-lymphoma." (PMID 23936541, 2013). "In addition, pSS patients with lymphoma display higher serum levels of CCL11 and CXCL13 compared with patients without lymphoma." (PMID 29707540, 2018). "Furthermore, when CSF CXCL13 concentrations were followed longitudinally in 7 patients with PCNSL, levels declined in all 5 individuals who responded to chemotherapy and increased in both cases where lymphoma progression occurred." (PMID 28603659, 2016).
lymphoma (continued). "Interestingly, the administration of anti-CXCL13 antibody has been shown to be promising in patients where the lymphoma does not regress after standard antibiotic treatment." (PMID 26657504, 2016). "Future studies should investigate the contribution of CXCL13 to the development of non-AIDS events and assess if plasma levels of CXCL13 can be used as a prognostic marker for the development of certain non-AIDS events including lymphoma." (PMID 30846990, 2019). "CXCL13 could not discriminate between the MR and pSS-NHL+ groups but could distinguish the LR from the MR group which may indicate a role of CXCL13 in the early stages of the pathophysiological process of lymphoma development." (PMID 32047959, 2020).
prostate carcinoma (44 papers, 2010 to 2025). A carcinoma that arises from epithelial cells of the prostate gland. "Higher amounts of B cells were discovered in the high-risk group because recruitment of the chemokine CXCL13 to B cells in PCa promotes the development of castration-resistant prostate cancer by generating lymphotoxin." (PMID 37742230, 2023). "Silica nanoparticles loaded with snake venom may cause apoptosis and limit proliferation in human prostate cancer cells, as well as dramatically lower the levels of numerous chemokines (including CXCL13) and their receptors (including CXCR5)." (PMID 34922542, 2021). "In mouse models of colon carcinoma, IL-6 and GM-CSF secreted by CAFs drive monocyte differentiation toward M2-like TAMs, whereas CXCL13 recruits lymphotoxin-expressing B cells to increase prostate cancer aggressiveness." (PMID 40562870, 2025). "CXCL13, also known as B lymphocyte chemoattractant (BLC) or B cell-attracting chemokine 1 (BCA-1), is produced by DCs, T follicular helper cells, prostate cancer cells, Jurkat cells, and cancer-associated myofibroblasts." (PMID 41445742, 2025). "CXCL13 is also an androgen-responsive gene and has been shown to be involved in androgen-induced prostate cancer." (PMID 36674726, 2023). "Tumor myofibroblasts express CXCL13, and TGF-β induced by hypoxia drives the expression of CXCL13, leading to accelerated malignant progression and castration-resistant prostate cancer development." (PMID 35625561, 2022). "Another mode by which hypoxia and TGF-β cooperate in promoting prostate cancer aggressiveness is the activation of myofibroblasts through chemokine (C-X-C motif) ligand 13 (CXCL13) expression." (PMID 35625561, 2022). "CXCL13-dependent cell invasion in prostate cancer (PCa) cells was significantly inhibited by the application of siRNA targeting Gαq and Gαi2, indicating that the CXCL13/CXCR5/Gαq signaling pathway regulates cellular chemotaxis." (PMID 35053457, 2022). "Other studies revealed that B cells recruited by CXCL13 into prostate cancer tumors promote the progression of androgen-deprived prostate cancer leading to accelerated malignant progression and drug resistance." (PMID 36217194, 2022). "It has been shown that hypoxia activates TGF-β signaling via HIF-1α to convert fibroblasts into myofibroblasts, which in turn induces C-X-C motif chemokine 13 (CXCL13) expression for B cell recruitment and metastatic progression of prostate cancer cells." (PMID 35884382, 2022). "Actually, CXCL13 was found to be positively correlated with IL-6 in prostate cancer, BPH and high-grade prostatic intraepithelial neoplasia, and involved in experimental autoimmune cystitis and interstitial cystitis." (PMID 36613500, 2022). "For example, CXCL13 expression in CAFs positively correlates with worse prostate cancer severity in prostate cancer patients and is elevated in response to ASRi and/or chemotherapy." (PMID 36671452, 2022). "Chronic hypoxia increases the expression of CXCL13 in adipocytes and promotes the metastasis of prostate cancer by increasing the expression of CXCL13 in tumor myofibroblasts." (PMID 34947813, 2021). "In accordance with Haibi et al44 reported in prostate cancer, CXCL13/CXCR5‐promoted cell migration and invasion was regulated by Src activation." (PMID 34427969, 2021). "CAFs release CXCL13 in prostate cancer and have a role in androgen-independent prostate cancer development." (PMID 34922542, 2021). "In vivo, IL-30 overexpression in primary tumors facilitates the recruitment of prostate cancer stem-like cells (PCSLCs) to CXCL13, creating a microenvironment convenient for lymph node and blood metastasis." (PMID 33110086, 2020). "B lymphocytes recruited by CXCL13 into the tumor site promote castration-resistant prostate cancer by producing lymphotoxin, which activates an IKKα-Bmi1 module in prostate cancer stem cells." (PMID 31395078, 2019).
prostate carcinoma (continued). "Recent discoveries linking up-regulation of the CXCL13:CXCR5 axis to the dissemination of prostate cancer stem-like cells to lymph nodes and bone marrow further support this concept." (PMID 31354634, 2019). "CXCL13 is elevated in serum of prostate cancer patients and was found to be a better predictor of prostate cancer than prostate-specific antigen (PSA)." (PMID 31354634, 2019). "For TIBs, few studies have shown that B cells produce lymphotoxin and promote the progress of androgen-resistant prostate cancer by activating the IKKα-BMI1 signal pathway in prostate cancer stem cells under the influence of chemokine CXCL13." (PMID 31662750, 2019). "Signaling studies revealed that DOCK2 (Dedicator of cytokinesis 2), ERK1/2, JNK and Akt signals mediate CXCL13 invasive and proliferative responses in prostate cancer cells." (PMID 31354634, 2019). "In prostate cancer, CXCL13 mediates MMPs expression and actives protein secretion in a CXCR5-dependent way." (PMID 30723697, 2018). "Expression of CXCR5, a corresponding receptor for CXCL13, was higher in prostate cancer cases, and the intensity of CXCR5 expression positively correlated with the Gleason score." (PMID 25912035, 2015). "Three regulatory networks, PI3 K/Akt, ERK/MAPK, and JNK/c-Jun pathways, are confirmed to be dramatically induced by CXCL13 in prostate cancer." (PMID 26161394, 2015). "CXCR5/CXCL13 is related to bone metastasis of prostate cancer." (PMID 41333471, 2025). "In addition, it has been found that the CXCL13 recruits B cells into prostate cancer tumors and activate the IκB kinase α-BMI1 module in cancer stem cells through the production of LT, thus promoting the progression of castration-resistant prostate cancer." (PMID 39744696, 2025). "Considering previous studies highlighting the importance of CXCL13 axis in B cell recruitment and our finding of CXCL13 downregulation in FOXA1 mutant prostate cancer, it is plausible to suggest that CXCL13 may be a contributing factor to these results." (PMID 37958805, 2023). "In a murine prostate cancer model, which exhibits PKCε overexpression and Pten deficiency, the release of CXCL13 by tumor cells was upregulated in a non-canonical NF-κB pathway, boosting tumor cells’ migratory properties." (PMID 34947813, 2021). "Similarly, in prostate cancer cell lines, the addition of CXCL13 increased expression of ECM remodeling genes." (PMID 33193299, 2020). "CXCL13 knockdown resulted in reduced prostate cancer and OSCC bone invasion in mouse models." (PMID 33193299, 2020). "Interestingly, androgen stimulates CXCL13 production in prostate cancer cells, and CXCL13 was found to be an androgen-responsive gene that contains a canonical androgen-responsive element in its promoter." (PMID 31354634, 2019). "Furthermore, CXCL13 produced by bone marrow endothelial cells in response to IL-6 was able to induce prostate cancer cell invasion in a CXCR5-dependent manner." (PMID 31354634, 2019). "However, the expression level of DOCK2 is positively correlated with the proliferation rate of CXCL13-induced prostate cancer cells." (PMID 31762818, 2019). "Depending on PI3Kp110, Src and FAK, the interaction of CXCR5 with its specific ligand—CXCL13, could promote prostate cancer cell invasion, migration, and differential matrix metalloproteinase (MMP) expression." (PMID 25990390, 2015). "CXCL13 may contribute significantly to breast tumor formation and mediate the progress of prostate cancer through activating JNK and ERK pathways." (PMID 26161394, 2015). "Serum CXCL13 was significantly higher in prostate cancer patients compared to patients with benign prostatic hyperplasia or high-grade prostatic intraepithelial neoplasia and normal healthy donors, suggesting that CXCL13 is a better predictor of prostate cancer than PSA." (PMID 25912035, 2015). "Several C-X-C motif (CXC) chemokines were upregulated in prostate cancer lung metastases, notably CXCL10, CXCL11, and CXCL13." (PMID 39146303, 2024).
prostate carcinoma (continued). "The CXCL13/CXCR5 axis promotes the proliferation and invasion of prostate cancer (PCa) cells by activating JNK, ERK, SRC/FAK, PI3K, and Akt." (PMID 34947813, 2021). "Studies have shown that CXCL13 recruits B cells that produce lymphotoxins; thereby activating IkB kinase α (IKK α) in prostate cancer stem cells which promotes progression of castration resistant prostate cancer." (PMID 31628349, 2019). "The gene ontology results further imply CXCL13 and CXCR5’s role in the development of prostate cancer." (PMID 31628349, 2019). "In this context, CXCL13 and CXCR5 appear to be highly relevant in prostate cancer cell proliferation, migration, and invasion, ultimately impacting disease progression and metastatic dissemination." (PMID 31354634, 2019). "Inhibition of CXCL13 or CXCR5 can impair the migratory and tumorigenic properties of prostate cancer cells." (PMID 30723697, 2018). "It is reported that CXCL13/CXCR5 axis promoted colon cancer growth and invasion via PI3K/AKT pathway, mediated prostate cancer cell proliferation through JNK and ERK signaling." (PMID 30723697, 2018). "Studies have shown chemokines like CXCL13 and CXCL16 independently enhance cell proliferation as well as invasive capacity of prostate cancer cells and human trophoblast cells." (PMID 25888629, 2015). "It has been also reported that CXCL13 increased migration and invasion of LNCaP and PC3 prostate cancer cells." (PMID 25912035, 2015). "In prostate cancer, activation of the nonclassical NF-κB signaling pathway promotes the secretion of CXCL13 in tumor cells." (PMID 40406143, 2025). "CXCL13-mediated NF-κB activation in B cells induces LT secretion, which enhances leukocyte infiltration and metastatic potential via the IKKα–BMI1 axis, particularly in androgen-deprived prostate cancer." (PMID 40562870, 2025). "CXCL13 recruits B cells to prostate tumors to promote castrate-resistant cancer progression by producing lymphotoxin, which activates an IκB kinase α (IKKα)-BMI1 module in prostate cancer stem cells." (PMID 34947813, 2021). "Though the regulatory role of CXCL13 has been proven to mediate the activation of JNK and MAPK pathways in prostate cancer invasion and migration, its modulating acts on Wnt/β-catenin signaling in HCC and the effect of Wnt/β-catenin pathway on CXCL13 was still obscure." (PMID 26161394, 2015). "Prostate cancer (PCa) cell lines and tissues differentially express CXCR5, which positively correlate with PCa progression, and mediate PCa cell migration and invasion following interaction with CXCL13." (PMID 23773523, 2013). "CXCL13 up-regulation in prostate cancer cells is driven by the non-canonical NF-κB pathway." (PMID 31354634, 2019). "Altogether, evidence indicates that a complex network of cellular interactions involving CXCL13 and CXCR5 integrate to promote prostate cancer cell autonomous and non-autonomous pathways." (PMID 31354634, 2019).
colorectal cancer (40 papers, 2015 to 2025). A primary or metastatic malignant neoplasm that affects the colon or rectum. "In 5-fluorouracil (5-Fu)-resistant colorectal cancer patients, serum CXCL13 is elevated, and a high CXCL13 concentration is associated with a worse clinical outcome." (PMID 34947813, 2021). "CXCL13 is critical to colorectal cancer pathogenesis, because CXCL13 deficiency and the blockade of CXCL13 signaling ameliorates disease progression." (PMID 34947813, 2021). "Extensive analysis of circulatory inflammatory factors at the time of colorectal cancer surgery, including cytokines, chemokines and interleukins, revealed CXCL13 as one of the factors associated with increased mortality." (PMID 31354634, 2019). "Also in colorectal cancer, CXCL13 expression mediates the infiltration of B, Tfh, Th1, and memory T cells, whereas the loss of CXCL13 expression due to chromosomal instability is associated with relapse." (PMID 34503058, 2021). "In colorectal cancer, genomic deletion of CXCL13 predicts a high risk of relapse." (PMID 26517519, 2015). "Elevated CXCL13 expression, influenced by miR‐934 in colorectal cancer, enhances tumor invasiveness." (PMID 40692663, 2025). "We additionally examined the expression of TNFRSF18 and CXCL13 in colorectal cancer and other tumours through the GEPIA database." (PMID 40770837, 2025). "For instance, M2-type macrophages can facilitate colorectal liver metastasis (CRLM) by secreting CXCL13, which subsequently activates the CXCL13/CXCR5/NF-κB/p65/miR-934 pathway in colorectal cancer (CRC) cells." (PMID 40034694, 2025). "In the T cell lineage, we found that CXCL13+T cells were more widely distributed in colorectal cancer tissues, and the proportion of infiltration was increased." (PMID 37675100, 2023). "CXCL13+BHLHE40+ Th1-like cells are potential markers of colorectal cancer immunotherapy and CXCL13 was suggested as a predictive biomarker for ICI response in bladder cancer." (PMID 35141160, 2022). "In another example, a newly defined T cell subset in colorectal cancer, a group of CXCL13+BHLHE40+ TH1-like cells, was found to be enriched in microsatellite-unstable tumors." (PMID 34405376, 2022). "A further study showed that polarized M2 macrophages mediate premetastatic niche formation and facilitate colorectal cancer liver metastasis by forming a positive-feedback loop of CXCL13/CXCR5/NFκB/p65/miR-934." (PMID 34947813, 2021). "The carcinogen azoxymethane/dextran sodium sulfate induces colorectal cancer in mice, whereas knockout of CXCL13 significantly inhibits the induction of colorectal tumorigenesis in vivo by these carcinogens." (PMID 34947813, 2021). "CXCL13 administration into the colonic submucosa of mice with colorectal cancer resulted in decreased tumor growth." (PMID 33193299, 2020). "In mouse colorectal cancer studies, direct CXCL13 administration was effective for impeding tumor growth." (PMID 33193299, 2020). "In agreement with this information, immunohistochemical analysis of advanced colorectal cancer specimens revealed significant elevation of CXCL13 and CXCR5 in tumors relative to normal tissue, which correlated with lymph node metastasis and neural invasion." (PMID 31354634, 2019). "In addition, CD8+ T cells exhibited elevated TNFRSF18 expression in colorectal cancer samples with liver metastasis, whereas CXCL13 was higher in CD8+ T cells from non‐metastatic colorectal cancer samples." (PMID 40770837, 2025). "Interestingly, knockout of CXCL13 inhibits azoxymethane/dextran sodium sulfate-induced colorectal cancer in mice." (PMID 34947813, 2021). "CXCL13 is also upregulated in human colorectal cancer and is secreted by dendritic cells." (PMID 34947813, 2021). "Furthermore, among colorectal cancer patients, increased intratumoral CXCL13 correlated with greater T cell and B cell tumor infiltration and prolonged patient survival." (PMID 33193299, 2020).